CD177 (CD177 molecule)
Diseases named in the same sentence as CD177 in open-access papers (continued):
Sharing a sentence is not in itself a finding about the gene and the disease.
bacteremia (2 papers, 2022 to 2024). "We next investigated the functional impact of CD177 in vivo using a translationally relevant model of acute bacteremia." (PMID 38517968, 2024). "CD177 is a surface marker expressed exclusively by neutrophils in 40–60% of healthy donors, its upregulation was observed in different inflammatory and infectious diseases and also in patients with bacteremia suggesting its role in the activation of PMNs by infection." (PMID 35533148, 2022).
biliary atresia (2 papers, 2025). A rare, biliary tract disease characterized by progressive obliterative cholangiopathy of the intra- and extrahepatic bile ducts, occurring in the embryonic/ perinatal period, leading to severe and persistent neonatal jaundice and acholic stool. "The use of N-acetylcysteine can reduce the percentage of CD177+ neutrophils and NETosis, indicating that it has potential therapeutic value for patients with biliary atresia, but the exact function of CD177+ neutrophils remains elusive in liver injury." (PMID 41142798, 2025). "In addition, CD177+ neutrophils were significantly increased in the liver tissue of patients with biliary atresia." (PMID 41142798, 2025). "Similarly, recent research uncovered that CD177+ neutrophils, in the biliary atresia (BA) model, can induce cholangiocyte death through the production of NETs." (PMID 41353336, 2025). "Recent studies point out that CD177+ neutrophils may aggravate inflammatory diseases such as inflammatory bowel disease and biliary atresia through NETs formation." (PMID 41353336, 2025).
Cirrhosis (2 papers, 2020 to 2023). A chronic disorder of the liver in which liver tissue becomes scarred and is partially replaced by regenerative nodules and fibrotic tissue resulting in loss of liver function. "This could also be the case in patients without cirrhosis who have septic shock because previous studies have shown that CD177 was most upregulated gene and protein in neutrophils from these patients." (PMID 33613548, 2020).
gastric adenocarcinoma (2 papers, 2013 to 2025). "Paradoxically, some data associate CD177 expression with improved prognosis in gastric adenocarcinoma, suggesting a dual role as both a carcinogenic driver and a prognostic biomarker." (PMID 41451221, 2025). "Furthermore, our results suggest that CD177 expression might be associated with a favorable prognosis of gastric adenocarcinomas in man." (PMID 23899160, 2013). "Immunohistochemistry reveals CD177 expression not only in tumour-infiltrating neutrophils but also in gastric adenocarcinoma cells, regardless of differentiation status." (PMID 41451221, 2025).
gastritis (2 papers, 2013 to 2019). Inflammation of the stomach. "Because they compared stage-matched groups to detect up- or down-regulated genes only by treatment of folic acid, it is unclear if Cd177 expression is associated with gastritis or dysplasia." (PMID 23899160, 2013). "This study was undertaken to further investigate the CD177 expression in CD177−/− mice, aiming at elucidating the relationship between CD177 expression and Hp-related gastritis." (PMID 31093484, 2019). "In the present study, the CD177 expression was further detected in CD177 KO mice, aiming at elucidating the relationship between CD177 expression and Hp-related gastritis." (PMID 31093484, 2019). "However, little is known about the role of CD177 in the Hp-related gastritis." (PMID 31093484, 2019). "In our previous study, results showed that CD177 expression in the gastric mucosa of patients with Hp-related gastritis was significantly higher than that of patients with non-Hp related gastritis." (PMID 31093484, 2019). "Our study showed that the CD177 expression was significantly higher in Hp-related gastritis than in non-Hp related gastritis." (PMID 31093484, 2019). "This study was undertaken to further investigate the CD177 expression in Helicobacter pylori- (Hp-) infected wild-type and CD177−/− C57BL/6 mice, which may be helpful to elucidate the relationship between CD177 and Hp-related gastritis." (PMID 31093484, 2019).
lymph node metastases (2 papers, 2013 to 2019). "Interestingly, we observed a significant difference in prognosis depending on the CD177 status in lymph node metastases collected during the primary surgical resection." (PMID 30377339, 2019).
non-small cell lung carcinoma (2 papers, 2017 to 2018). A group of at least three distinct histological types of lung cancer, including non-small cell squamous cell carcinoma, adenocarcinoma, and large cell carcinoma. "CD177 antigen has also been identified as a poor prognostic factor in patients with non-small cell lung cancer." (PMID 29681787, 2018).
prostate tumors (2 papers, 2018). "Notably, markers of chronic inflammation, such as CD3 receptors or CD68, are strongly correlated with NKX3.1 status in human prostate tumors, which is not the case for markers of acute inflammation such as CEACAM8 or CD177." (PMID 30266798, 2018).
renal carcinoma (2 papers, 2021 to 2022). A carcinoma arising from the epithelium of the renal parenchyma or the renal pelvis. "There was a negligible expression of CD177 on conventional CD4+ T cells (Tconv) in breast and renal cancers." (PMID 34599187, 2021).
skin infection (2 papers, 2015 to 2021). An inflammatory process affecting the skin, caused by bacteria, viruses, parasites, or fungi. "We examined the role of CD177 in neutrophil accumulation using a skin infection model with Staphylococcus aureus." (PMID 25359465, 2015). "To examine the role of CD177 in a bacterial infection model, we used a mouse model of Staphylococcus aureus skin infection." (PMID 25359465, 2015).
thyroid cancer (2 papers, 2024). "Most of the genes showed the same trend as transcriptomics, and in particular, CD177, HSPA1A, HSP1B, and S100A12 were significantly increased in advanced thyroid cancer compared to in indolent thyroid cancer." (PMID 38719807, 2024). "CD177, a marker of the proinflammatory neutrophil subset, and CD44, which plays an important role in neutrophil adhesion and migration, were upregulated both in UTC and advanced-stage thyroid cancer." (PMID 38719807, 2024).
AIDS (1 paper, 2026). A syndrome resulting from the acquired deficiency of cellular immunity caused by the human immunodeficiency virus (HIV). "Targeting CD177 represents a superior therapeutic strategy for NLRP3-AIDs, including IL-1β-refractory cases." (PMID 41898699, 2026).
brain injury (1 paper, 2020). Acute and chronic (see also brain INJURIES, CHRONIC) injuries to the brain, including the cerebral hemispheres, CEREBELLUM, and brain STEM. "In the cortex and striatum, Cd177 upregulation began 24 h after TBI, was the highest on the 4th day and remained elevated until the 7th day after traumatic brain injury when compared to that of sham-operated animals." (PMID 33375205, 2020).
cardiac arrest (1 paper, 2025). Cessation of breathing and/or cardiac function. "We observed that neutrophils had different expression levels of CD177, CD11b, and BLT-1 after cardiac arrest compared with those in the control group." (PMID 40743049, 2025).
Fever (1 paper, 2016). Body temperature elevated above the normal range. "CD177 is a cell surface glycoprotein expressed by subpopulations of neutrophils, but the correlation coefficient with neutrophil counts in the AdjuVIT active TB and Fever cohort samples was only 0.23." (PMID 27734027, 2016).
fungal infection (1 paper, 2020). "We therefore assume that the overrepresentation of CD177 in both infected humans and mice is a consequence of fungal infection and not the effect of myeloid disorders or treatments, but that CD177 would only be useful as a marker for infection if neutrophil counts are within a certain range." (PMID 33043780, 2020).
gastric tumor (1 paper, 2013). "Thus, there is a possibility that CD177 also acts as a regulator of adhesion and migration of neoplastic cells in gastric tumor." (PMID 23899160, 2013).
intestinal tumors (1 paper, 2025). "In general, CD177 + neutrophils are new indicators for monitoring the good prognosis of intestinal tumors." (PMID 41142798, 2025). "Furthermore, CD177+ neutrophils may serve as an independent prognostic factor for survival outcomes and a potential therapeutic target in intestinal tumors." (PMID 41142798, 2025).
leprosy (1 paper, 2024). Leprosy is a chronic infectious disease affecting primarily the skin and peripheral nervous system. "Supernatants of blood cells stimulated in vitro with Mycobacterium leprae sonicate showed higher levels of CD177 compared to the level of untreated cells, indicating that the leprosy bacillus can activate neutrophils expressing CD177." (PMID 38715615, 2024).
myocarditis (1 paper, 2023). Myocarditis is a condition that is characterized by inflammation of the heart muscle (myocardium). "Clinically relevant pathways, such as those of the inflammasome in ICI-induced myocarditis or the neutrophil activation cascade in gastrointestinal irAEs, have been identified through the overexpression of type 5 and 6 guanylate binding proteins and CD177 and CEACAM1 genes, respectively." (PMID 36900420, 2023).
Neonatal sepsis (1 paper, 2021). Systemic inflammatory response to infection in newborn babies. "Hence, the lower methylation levels observed in the promoters of genes involved in neutrophil activation (i.e., ATP8B4, LRG1, TREM1, PRTN3, S100A8, ELANE, and CD177) illustrates the role of DNAm in innate immunity in neonatal sepsis." (PMID 33659006, 2021).
peritonitis (1 paper, 2015). Inflammation of the peritoneum (tissue that lines the abdominal wall and covers most of the organs in the abdomen). "Since it was reported that CD177− and CD177+ neutrophils accumulate similarly in the peritoneal cavity of human peritonitis patients, we included a thioglycollate-induced peritonitis model to examine the effect of CD177 on neutrophil accumulation into the peritoneal cavity." (PMID 25359465, 2015). "However, a recent study indicated that CD177- and CD177+ neutrophils accumulate similarly in the peritoneal cavity of human peritonitis patients, suggesting that CD177 expression in neutrophils provides no transmigration advantage into this site." (PMID 25359465, 2015).
polycythemia (1 paper, 2016). Abnormally high mass or concentration of red blood cells in the blood, either due to an increase in erythropoiesis or a decrease in plasma volume. "CD177 (also known as neutrophil specific antigen B1 [NB1], human neutrophil antigen 2a [HNA-2a], and polycythemia rubra vera 1 [PRV1]) is a 56–64 kDa protein belonging to the Ly-6 family, and is expressed exclusively on neutrophils by glycosylphosphatidylinositol (GPI)-linkage." (PMID 27227454, 2016).
renal clear cell carcinoma (1 paper, 2025). "The neutrophil-associated marker CD177 is also enriched on Treg cells in renal clear cell carcinoma patients with poor prognoses; antibody-mediated blockade or Treg cell-specific deletion of CD177 decreases Treg cell accumulation in tumors and improves tumor control." (PMID 40468052, 2025).
septic shock (1 paper, 2023). Shock caused by infection; frequently caused by gram negative bacteria, although some cases have been caused by other bacteria, viruses, fungi, and protozoa; characterized by fever, chills, tachycardia, tachypnea, and hypotension. "Higher expression levels of CD177 and MMP8 proteins were also observed in the PBMCs isolated from septic shock patients than from control participants." (PMID 37359526, 2023). "CD177, CLEC5A, CYSTM1, MCEMP1, MMP8, and RGL4 were identified as hub genes, which were of considerable value in the early diagnosis of septic shock patients." (PMID 37359526, 2023). "In addition, higher expression levels of CD177, CLEC5A, CYSTM1, MCEMP1, MMP8, and RGL4 messenger RNA (mRNA) were observed in peripheral blood mononuclear cells (PBMCs) isolated from septic shock patients than from healthy donors." (PMID 37359526, 2023).
T cell deficiency (1 paper, 2022). "In contrast to T cell deficiency, the recurrent tumors were significantly enriched for markers of tumor-associated neutrophils (TANs; eg., CD177, ELANE), tumor-associated macrophages (TAMs; eg., MRC1, CD68), and immune suppressive myeloid cells (MDSCs; eg., ARG1, CXCR4)." (PMID 35919862, 2022).
tumor (224 papers, 1998 to 2025). "Treg cell-specific CD177 deficiency affects tumor growth and the number of TI Treg cells, highlighting the heterogeneity of TI Treg cells and the critical role of CD177 in their immunosuppressive function." (PMID 41035074, 2025). "Studies have shown that CD177-deficient Treg cells reduce tumor growth and TI-Treg frequency in mice." (PMID 39751938, 2025). "Collectively, we observed a sex disproportional regulation of genes mechanistically linked to tumor growth, and we confirmed the cRaf-dependent regulations of CD177 and NQO1 in females LC patients." (PMID 38245882, 2024). "Secondly, the differential expression and mutational burden of the CD177 gene had a more prominent effect on the prognosis of tumor patients." (PMID 37528394, 2023). "CD177 is mostly expressed in neutrophils, and is upregulated in tumor tissues of patients with colitis associated cancer (CAC)." (PMID 33193652, 2020). "Further studies are needed to clarify the association between CD177 expression in gastric epithelial cells and tumor progression." (PMID 23899160, 2013). "Here the authors perform transcriptome profiling of immune cells from patients with renal clear cell carcinoma to find a Treg signature that correlates with poorer prognosis, with CD177 being implicated as the main mediator for related alterations in Treg activity and tumor outcome." (PMID 34599187, 2021). "Comparing tumor-infiltrating versus blood Treg cells, we identified some common shared signature genes of tumor-infiltrating Treg cells, including some genes whose protein products are targetable such as CD177 and BCL2L1 (encoding BCL-XL)." (PMID 34831009, 2021). "All MSI-H CRCs were subjected to digital pathology-based quantification of CD3 + /CD8 + /CD4 + /FoxP3 + /CD68 + /CD204 + /CD177 + tumor-infiltrating immune cells using whole-slide immunohistochemistry." (PMID 39235590, 2024). "CD177 modulates the function and homeostasis of tumor-infiltrating regulatory T cells, one of the major immunosuppressive cell types in cancer." (PMID 37359526, 2023). "CD177 has been addressed by many tumor-related studies, and some experiments have verified its expression differences." (PMID 37528394, 2023). "We performed qRT-PCR validation on five genes and found that the expression of the CD177 gene in samples of tumor and normal tissues was more significant and stable than the other four genes." (PMID 37528394, 2023). "Our results showed that AML and CML differ in the expression of GBF1, CD177, OLFM4 and peptidylprolyl isomerase B (PPIB) implicated in the intercellular interactions and chemotaxis regulation to regulate tumor cell migration and invasion." (PMID 36230605, 2022). "Treg-specific Cd177 deletion resulted in reduced tumor growth, similarly as in the germline Cd177 KO mice." (PMID 34599187, 2021). "CD177 protein was detectable on Treg cells from various tissues – including tumor, lung, spleen, and thymus of WT tumor-bearing mice with the highest expression from TI Treg cells." (PMID 34599187, 2021). "Neutrophils expressing CD66b, CD11b, PD-L1, and high levels of CD170 represent the pro-tumor subtype, whereas CD66+, CD11b+, CD170 low, and CD177+ neutrophils have an anti-tumor role." (PMID 34386431, 2021). "In sum, starting from the unbiased elucidation of the PDPN co-receptome, our work provides insights into PDPN functions and reveals the PDPN/CD177 axis as a possible modulator of fibroblast physiology in the tumor microenvironment." (PMID 34879110, 2021). "Mechanistically, blocking CD177 reduces the suppressive activity of Treg cells in vitro, while Treg-specific deletion of Cd177 leads to decreased tumor growth and reduced TI Treg frequency in mice." (PMID 34599187, 2021). "We also purified Treg cells from tumor-bearing control or Treg-specific Cd177-KO mice (cKO) and confirmed the similar expression level of FoxP3." (PMID 34599187, 2021).